INS (insulin)
Diseases named in the same sentence as INS in open-access papers (continued):
Sharing a sentence is not in itself a finding about the gene and the disease.
Anorexia (continued). "Hematocrit, insulin, ghrelin, and corticosterone levels did not resemble shifts typically observed in patients with anorexia, though decreases in leptin levels aligned with human reports." (PMID 31481515, 2019). "Furthermore, the reverse IVW estimator did not indicate evidence of an effect from AN to fasting insulin (P = 0.986), although there was weak evidence of a negative relationship between anorexia liability and HbA1c, as described in the previous sections." (PMID 32920595, 2021). "As the negative relationship between insulin and anorexia is also evidenced using a genomic correlation approach, there is a need to investigate shared genes and biological pathways which may explain this association." (PMID 32920595, 2021). "However, not all PD patients suffer anorexia under similar conditions, suggesting that factors like peritoneal glucose absorption and insulin metabolism, or dialysis clearance, influence on appetite control." (PMID 31191339, 2019). "These include anorexia, impaired protein metabolism and transport, oxidative stress, production of nonspecific inflammatory cytokines, resistance to insulin, volume overload, metabolic acidosis, nutrient losses through the hemodiafilter, and patient comorbidities." (PMID 20346168, 2010). "In mandarin fish, anorexia after feeding high-carbohydrate diets might be attributed to high plasma glucose, which could not be transformed into glycogen or lipid and no enhanced insulin to down-regulate the glucose level." (PMID 32636801, 2020). "Taken together, the KDE was well tolerated, attenuated anorexia, altered systemic metabolism, attenuated indices of tumor burden, and reduced skeletal muscle atrophy without changing circulating IGF‐1 and insulin levels, illustrating a unique and multifaceted anti‐CACS therapy." (PMID 32239651, 2020).
glioma (45 papers, 2011 to 2026). A benign or malignant brain and spinal cord tumor that arises from glial cells (astrocytes, oligodendrocytes, ependymal cells). "Restoration of neuronal insulin activity is sufficient to rescue synapse loss and to delay the premature death caused by glioma." (PMID 33526430, 2021). "Iron blocks the inhibition of insulin of glucose production by the liver and also insulin causes the increased ferritin synthesis in cultured glioma cells." (PMID 30043289, 2018). "Among the clinical factors, insulin use was identified as a significant factor for the association between WC and the risk of glioma (adjusted HR [95% CI]; 0.740 [0.485, 1.130] in insulin users vs. 1.174 [1.043, 1.322] in non-insulin users, P for interaction = 0.034)." (PMID 36928679, 2023). "It has been proposed that the associations of body mass, height and physical activity with risk of glioma may be related to early life energy balance, and subsequent influences on circulating insulin levels." (PMID 35184245, 2022). "Insulin in neurons can prevent synaptic loss and delay death due to glioma, and intestinal flora can improve insulin resistance by producing the metabolite SCFA, and the levels of certain bacteria, such as Collinsella, are highly correlated with serum insulin levels." (PMID 36497459, 2022). "Moreover, though glioma drug development has focused on IGFI signaling, it remains unproven which insulin signaling compound and its associated coregulators contribute to the greatest glioma progression." (PMID 25884993, 2015). "Inhibition of tumor cell metabolism: Metformin can reduce intracellular glucose levels and insulin signaling, thereby inhibiting the glycolysis process of tumor cells to further weaken the growth and proliferation of glioma cells." (PMID 39944825, 2025). "Building on these findings, insulin was utilized as a differentiation agent in our previous research to induce astrocytic properties in C6 glioma cells." (PMID 40016145, 2025). "Intraperitoneal application of AuNPs (spherical, 20 nm modified with insulin and chemotherapeutic cetuximab) for successful glioma therapy, is possible." (PMID 39711799, 2024). "Compared with m7Gcluster-B, m7Gcluster-A presented a significant survival advantage with inositol phosphate metabolism, phosphatidylinositol, glioma, neurotrophin, ErbB, mTOR, insulin, Wnt signaling pathways as well as other enrichment pathways." (PMID 36998056, 2023). "Conversely, the mitigation of insulin levels in non-CNS cancer cells can inhibit oncogenesis, while insulin-induced proliferation in these cells can be reversed by inhibiting PAM activation." (PMID 33472174, 2021). "KEGG Pathway analysis indicated that several pathways were consistent, including Glioma, Insulin signaling pathway, Thyroid hormone signaling pathway, cell cycle, pathways in cancer, etc.." (PMID 31602253, 2019). "For upregulated miRNAs, the enriched KEGG pathways contained pathways in cancer, focal adhesion, glioma, neurotrophin signaling pathway and insulin signaling pathway." (PMID 30268144, 2018). "In order to treat glioma by targeting the insulin signaling pathway, the detailed molecular mechanisms linking this signaling pathway to cancer growth need to be understood." (PMID 25884993, 2015). "Some roles for HIF1α in glioma progression and in the insulin signaling pathway specifically have been identified: HIF1α promotes malignant cell growth, and elevated expression of HIF1α has been strongly correlated to tumor malignancy." (PMID 25884993, 2015). "For example IGFBP7 also binds directly to insulin and in an artificial cell system it was recently demonstrated that glioma cell growth can be mediated by expressing IGFBP7." (PMID 21943323, 2011). "Moreover, one study suggested that metformin’s ability to decrease insulin signaling contributes to its pro-apoptotic effects, making it a potential agent against glioma cell proliferation." (PMID 39944825, 2025).
glioma (continued). "By effectively controlling hyperglycemia and insulin levels, metformin may indirectly improve the prognosis in diabetic glioma patients by limiting cancer-promoting conditions." (PMID 39944825, 2025). "GABAergic synapses, insulin secretion, morphine addiction, nicotine addiction, and synaptic vesicle cycle were significantly inhibited, suggesting that immune dysfunction plays an essential role in glioma development." (PMID 36506527, 2022). "In addition, cell cycle progression in astrocytes can be modulated by hyperglycemic conditions, while proliferation and survival of CNS cancer cells is inherently coupled to insulin-dependent PAM signaling." (PMID 33472174, 2021). "Furthermore, experiments conducted in insulin-stimulated IRS-1-transfected glioma cell showed high phosphorylation levels of AKT, ERK1/2 and overexpression of Grb2 resulting in increased cell viability." (PMID 33604294, 2020). "So far, it is unclear whether exogenous insulin or insulin secretagogues affect the risk of glioma because other studies showed that exogenous insulin use itself did not significantly affect glioma risk." (PMID 36928679, 2023). "Similarly, the IPA analysis has shown that the insulin treatment upregulated signaling pathways that promote vascular development such as glioma invasiveness signaling, glioblastoma multiforme signaling, factors promoting cardiogenesis in vertebrates, and inhibition of matrix metalloproteases." (PMID 35974022, 2022). "However, other transcription factor(s) that reduce SLC7A1 transcriptional activity, such as the C/EBP homologous protein 10 (CHOP) as reported in C6 rat glioma cells, may be involved in mediating insulin effects." (PMID 25875935, 2015). "Glioma cells can become more vulnerable to TMZ-induced cell death by decreasing pro-survival pathways, which is achieved by lowering insulin/IGF-1 signaling." (PMID 38891882, 2024). "For Metagene 10, the KEGG pathway enrichments study of T2D gene expression data revealed insulin signaling pathway (pvalue <0.05, FDR = 4.80E−12) as one of the significant pathways among glioma and ErbB signaling pathway." (PMID 36711310, 2023). "Using the KEGG PATHWAY database, we observed that a significant number of genes from the cell cycle, Hippo, WNT, TGFβ, NOTCH, Insulin, MAPK, and Glioma signaling pathways were highly expressed in adult RPE." (PMID 30846751, 2019). "Subgroup analysis showed that patients with larger WC had a consistently higher incidence of glioma than their lean counterparts, except for insulin users (insulin user vs. nonuser, P for interaction = .03)." (PMID 36928679, 2023). "Physical activity might influence the process of carcinogenesis through lowering free insulin and IGF-1 levels; however, it seems that the binding of these molecules to their proteins is very low in glioma." (PMID 35045870, 2022). "It should be noted that, given that high concentration of insulin can also activate IGF1R, the minimal media used for nonadherent growth assay were devoid of insulin, which was otherwise routinely added for glioma cell culture in many studies." (PMID 33173731, 2020). "In addition, in gliomas cells, PPAR gamma is downregulated, leading to a decrease in insulin sensitivity and an increase in neuroinflammation." (PMID 28620312, 2017). "Given that BA has previously been implicated in blocking diverse canonical YY1/FAS, ERβ, insulin/IGF‐1, MAPK/ERK and Notch signalling pathways in different pathological models, we next investigated which pathway was responsible for UBE2T downregulation in glioma." (PMID 41486508, 2026). "Although previous studies have reported that interruption of the PI3K class I/AKT/mTOR pathway with siRNAs or pharmacological inhibitors can induce autophagy in human glioma cells, we observed that under our conditions insulin does not inhibit autophagy in the mock-treated U87MG cells." (PMID 24349488, 2013).
peripheral arterial disease (45 papers, 2006 to 2026). A disorder of the arteries supplying the upper and lower extremity and the visceral organs. "In a subgroup analysis considering the primary endpoint, an interaction was observed regarding a history of peripheral artery disease and a prescription of insulin." (PMID 39469391, 2024).
alcoholism (44 papers, 2009 to 2025). "Disarticulation and bilateral amputations were associated with age ≥67 years, male gender, alcoholism, and insulin use adjusted by previous knowledge of DM, cardiovascular disease, and specific primary healthcare guidelines." (PMID 32715137, 2020). "Alterations in metabolism (e.g., mitochondrial dysfunction, insulin/glucose dysregulation), circadian cycle, sleep disruptions, and inflammation have long been associated with chronic alcohol use, abuse, and alcoholism." (PMID 30319684, 2018). "C group, 78 DEPs were enriched (18 upregulated and 60 downregulated), with dominant pathways including the citrate cycle (TCA cycle), dopaminergic synapse, insulin signaling pathway, alcoholism, insulin resistance, and plant–pathogen interactions." (PMID 40895305, 2025). "Due to interest in insulin-based medications for alcohol use disorder, we examined insulin/insulin-like growth factor 1 (IGF-1) genes in the prelimbic (PL) and infralimbic (IL) medial prefrontal cortex, a region linked to alcohol dependence and cognition." (PMID 41400881, 2025). "Although the central mechanisms linking insulin/IGF-1 signaling to alcohol dependence remain unclear, we speculate that the long-term consequence of alcohol consumption suppresses these systems which may contribute to changes in cognitive behavior." (PMID 41400881, 2025). "Additionally, the advancement of HCC is significantly influenced by AMPK signaling, insulin signaling pathways in rank 2, alcoholism, and hepatitis B." (PMID 40546347, 2025). "Pathway analysis of these 107 COPD-associated genes identified biological pathways that were enriched (FDR < 0.05) for regulation of actin cytoskeleton, insulin signaling and resistance, focal adhesion, phagosome, immune processes, infections and diseases, alcoholism, long-term depression." (PMID 36574990, 2023). "The cortisol values were depressed in the participants with alcohol dependence from the second blood sample to the end of the study, and also showed significantly larger and more rapid glucose and insulin responses following the consumption of the placebo beer." (PMID 36235578, 2022). "- a history of alcohol abuse or drugs including insulin, chemotherapy, antacids or diuretics." (PMID 19284691, 2009). "We hypothesize that this protective effect is not due to a direct role of ALDH2 in insulin function but rather a behavioral consequence, as carriers of the A allele are more likely to abstain from alcohol consumption due to alcohol intolerance." (PMID 40699860, 2025). "Finally, patients with a reduced capacity for insulin production for any reason, such as alcoholism, cystic fibrosis, or chronic pancreatitis to name a few, are at the highest risk of EDKA because of their impaired ability to counteract these combined challenges." (PMID 41020054, 2025). "Disulfiram (DSF), an FDA-approved drug used to treat alcoholism, was previously shown to harbor metabolic protective effects against HFD by reducing weight gain, liver steatosis, and promoting insulin responsiveness." (PMID 39069555, 2024).
inflammatory bowel disease (44 papers, 2009 to 2025). A spectrum of small and large bowel inflammatory diseases of unknown etiology. "SRB have been of increasing interest in human health, due to their positive effects on weight loss and insulin sensitivity, as well as possible detrimental effects in inflammatory bowel disease due to increased H2S production." (PMID 30704054, 2019). "FMT is a therapeutic option for inflammatory bowel disease induced by Clostridium difficile infection, and recent studies have reported metabolic improvements, including insulin sensitivity, with FMT." (PMID 31551944, 2019). "Previous studies reported that the consumption of microencapsulated sodium butyrate reduced signs of clinical severity of symptomatic uncomplicated diverticular disease, irritable bowel syndrome or inflammatory bowel disease, improved insulin sensitivity and reduced blood pressure in human patients." (PMID 40647300, 2025). "We used acute and chronic murine models of inflammatory bowel disease (IBD) to evaluate whether insulin influences the progression of colitis." (PMID 37491256, 2023). "Causality can be inferred when, for example, fecal transplantation (and thus microbiota inoculation) in human subjects is used successfully to treat inflammatory bowel disease (IBD—primarily ulcerative colitis) and insulin sensitivity associated with metabolic syndrome." (PMID 23483075, 2013). "Moreover, activation of GPR39 has been demonstrated to promote wound healing, ameliorate symptoms of inflammatory bowel diseases, dampen epileptic seizure activity, reduce anxiety-like behaviors and regulate insulin secretion and malignant progression of several cancers." (PMID 34645465, 2021). "In inflammatory bowel diseases, a contribution of EECs to pathogenesis is indicated by autoantibodies affecting EEC function and general disease symptoms like insulin resistance and altered intestinal motility." (PMID 41047099, 2025). "The prospective interventional substudy proved that anti-TNF therapy has a favorable effect on insulin sensitivity in nondiabetic, nonobese patients with inflammatory bowel disease." (PMID 29576769, 2018).
myocardial ischemia (43 papers, 2005 to 2025). A disorder of cardiac function caused by insufficient blood flow to the muscle tissue of the heart. "Studies have shown that the extracellular environment such as high glucose, high insulin, and insulin resistance of cardiomyocytes in patients with myocardial ischemia is an important cause of poor prognosis." (PMID 31886285, 2019). "This study described the following independent risk factors as predictor of future cardiac events: use of insulin, ventricular ejection fraction in peak exercise and, similar to our study, myocardial ischemia detected by EE." (PMID 19480653, 2009). "MG53 is involved in the protective effects against myocardial ischemia/reperfusion injury, which also regulates insulin sensitivity and energy metabolism in skeletal muscle." (PMID 40801027, 2025). "Protein palmitoylation has been reported to be involved in the regulation of insulin resistance, myocardial ischemia‐reperfusion injury, and other CVD." (PMID 39665133, 2025). "● Decreased elevated levels of renal oxidative stress, glomerular filtration rate, insulin sensitivity, and pathological score;● Ameliorated myocardial ischemia-reperfusion-induced renal injury." (PMID 37687031, 2023). "For example, miR-320 participates in the cardioprotective effect of insulin against myocardial ischemia via downregulating survivin." (PMID 34040522, 2021). "Myocardial ischemia and HCM share the following elements: calcium, ATP, AMPK, PKA, AKT cross-talking with ERK, glucose, INS, SIRT1 gene encoding sirtuin 1, NF-κB, TNF, reactive oxygen species, inflammatory response, and apoptosis." (PMID 34440529, 2021). "An animal study using cardiac magnetic resonance showed that FPG variability induced by intermittent insulin injection during the peri-procedural period led to adverse ventricular enlargement after experimental myocardial ischemia/reperfusion injury." (PMID 32878604, 2020). "Glycyrrhizic acid also exhibits cardioprotective effects against isoproterenol-induced myocardial ischemia in rats and improves lipoprotein lipase expression, insulin sensitivity, serum lipid, and lipid deposition in high-fat diet-induced obese rats." (PMID 28099940, 2017). "Myocardial ischemia is followed by functional, biochemical and morphological consequences, including the inhibition of insulin signaling." (PMID 28036029, 2016). "Insulin protects cardiomyocytes from myocardial ischemia/reperfusion (MI/R) injury through activating Akt." (PMID 27019292, 2016). "It is also well known that insulin exerts a salutary preconditioning effect against myocardial ischemia/reperfusion injury." (PMID 24371503, 2013). "The beneficial effect of an infusion of insulin during myocardial ischemia has been suggested by a small number of clinical studies, although they lacked a randomized design and were not conclusive." (PMID 17284309, 2007). "In line with these conclusions, there is increasing evidence that IR indices that are not based on insulin are linked to myocardial ischemia." (PMID 40547531, 2025). "Furthermore, this discussion highlights the mutual interaction between the endocrine and cardiac systems, where CAD produced by myocardial ischemia worsens insulin resistance through complex molecular pathways." (PMID 38269234, 2023). "It has been demonstrated that SH could raise the concentration of free fatty acids through oxidative stress response and insulin resistance, which could directly impact the heart’s normal rhythm, especially in patients with pre-existing myocardial ischemia." (PMID 37118670, 2023). "Ultimately, preoperative insulin use may improve postoperative myocardial ischemia and reduce inflammatory responses, thereby reducing POAF." (PMID 36042409, 2022). "In view of the possible beneficial effect of insulin on myocardial ischemia, this difference in treatment may explain the different prognosis." (PMID 34912898, 2021).